NHERF1 (NHERF family PDZ scaffold protein 1)
Diseases named in the same sentence as NHERF1 in open-access papers (continued):
Sharing a sentence is not in itself a finding about the gene and the disease.
cervical carcinoma (continued). "Gene Set Enrichment Analysis (GSEA) on the TCGA cervical cancer dataset showed that the genes related to cisplatin resistance were correlated with NHERF1 expression." (PMID 28085111, 2017). "Also, NHERF-1 has been found to play a role in cisplatin resistance of cervical cancer cells by inhibiting AKT and ERK signaling pathways." (PMID 32695664, 2020). "NHERF1 was discovered as putative interaction partners of MRP4 in cervical cancers." (PMID 32164629, 2020). "Incessant EGFR activation by NHERF-1 correlates with poor prognosis in cervical cancer." (PMID 32695664, 2020). "Moreover, loss of NHERF-1 expression in the cervical cell line promoted cellular adhesion, wound healing, and invasion, indicating NHERF-1 as a plausible therapeutic target for cervical cancer patients." (PMID 32695664, 2020). "NHERF1 was able to enhance the effects of chemo-drugs in breast and cervical cancer cells." (PMID 32164629, 2020). "The protein levels of NHERF1 were also robustly reduced in cervical cancer specimens." (PMID 29867145, 2018). "It is likely that downregulation of NHERF1 may result in development of cervical cancer by promotion of β-catenin-mediated proliferation." (PMID 29867145, 2018). "However, when ACTN4 expression was knocked down by siRNA, NHERF1 had less effect on the cervical cancer cell proliferation." (PMID 29867145, 2018). "Thus, the regulation of β-catenin protein levels by NHERF1 was further analyzed in cervical cancer cells." (PMID 29867145, 2018). "Low level of NHERF1 may contribute to the development of cervical cancer and indicated poor prognosis of cervical cancer patients." (PMID 29867145, 2018). "The molecular mechanisms of NHERF1 in the regulation of Wnt/β-catenin signaling and the proliferation of cervical cancer were largely unknown." (PMID 29867145, 2018). "We next tested whether NHERF1 expression could affect cisplatin sensitivity in cervical cancer cells." (PMID 28085111, 2017). "Therefore, NHERF1 may potentially serve as a biomarker for prognosis evaluation or a therapeutic target of cervical cancer." (PMID 29867145, 2018). "Therefore, it is likely that the worse prognosis of HPV-inactive cervical cancer patients may be attributed to robustly low levels of NHERF1." (PMID 29867145, 2018). "Thus, it is highly possible that NHERF1 may inhibit proliferation of cervical cancer cells through regulation of ACTN4 protein expression." (PMID 29867145, 2018). "Our data suggest that NHERF1 may enhance cisplatin chemosensitivity in cervical cancer." (PMID 28085111, 2017). "For example, HPV-16 E6 oncoprotein, following a decrease in Na + /H + exchanger regulatory factor 1 (NHERF1), increases ACTN4 actin cytoskeletal protein level and subsequently enhances actin polymerization, migration, and invasion of cervical cancer cells." (PMID 36681850, 2023). "This possibility needs to be verified by comparison of the mRNA and protein levels of NHERF1, activation status of Wnt/β-catenin signaling, and prognosis of HPV-active cervical cancer in the future study." (PMID 29867145, 2018). "Downregulation of NHERF1 protein then leads to oncogenenic proliferation upon upregulation of ACTN4 and activation of Wnt/β-catenin signaling in HPV-active cervical cancer." (PMID 29867145, 2018). "Furthermore, the authors have shown that NHERF1 inhibits ACTN4-mediated stabilization of β-catenin, activation Wnt/β-catenin signaling, and hence suppresses the proliferation of cervical cancer cells." (PMID 31766144, 2019). "Upon depletion of ACTN4 expression, NHERF1 failed to inhibit the clonogenic capacity of cervical cancer cells." (PMID 29867145, 2018). "A negative association between NHERF1 expression and levels of ACTN4 and β-catenin was found in mouse xenograft model and cervical cancer specimens." (PMID 29867145, 2018).
cervical carcinoma (continued). "All these findings suggest that NHERF1 may suppress Wnt/β-catenin signaling activation via a decrease in ACTN4 levels to elicit anti-proliferation and tumor-suppressive effects in cervical cancer." (PMID 29867145, 2018). "The expression of c-Myc and TCF-1, downstream target genes of Wnt/β-catenin signaling, was analyzed after treating the cervical cancer cells with IWR-1-endo, a Wnt/β-catenin signaling inhibitor, in the presence or absence of NHERF1 expression." (PMID 29867145, 2018). "However, clonogenic growth was not affected by NHERF1 when IWR-1-endo was applied, indicating that NHERF1 inhibition of cervical cancer cell proliferation was mediated by suppression of Wnt/β-catenin signaling." (PMID 29867145, 2018).
colorectal cancer (10 papers, 2011 to 2023). A primary or metastatic malignant neoplasm that affects the colon or rectum. "High expression of VEGFR2 was associated with shorter overall survival of patients with colorectal cancer depending on the low NHERF1 expression." (PMID 27999191, 2017). "Recently, it was also reported that the expression of NHERF1 was strongly correlated with higher expression of HIF-1α in colorectal cancers, suggesting association with the tumor hypoxia microenvironment." (PMID 27999191, 2017). "The oncogenic role of ectopic expression of Na+/H+ exchanger regulatory factor 1 (NHERF1) was recently suggested in colorectal cancer, where it was implicated in playing a role in the tumor hypoxia microenvironment." (PMID 27999191, 2017). "Similar progressive NHERF1 changes as in CP tumors, with loss of apical plasma membrane expression and cytoplasmic accumulation have been noted previously in the colorectal cancer transformation sequence." (PMID 27229317, 2016). "We have previously shown that NHERF1 deficiency in mice induces structural abnormalities of the intestinal apical PM that translate into defective epithelial morphogenesis with loss of apico-basal polarity and epithelial-mesenchymal transition in colorectal cancer cells." (PMID 25775275, 2015). "During the early stages of carcinogenesis in colorectal cancers, nuclear NHERF1 was correlated with poor prognosis." (PMID 32164629, 2020). "Nuclear NHERF1 was identified in colorectal cancer of early stages and was believed to participate the onset of the malignant phenotype during carcinogenesis leading to poor prognosis." (PMID 32164629, 2020). "TCF1 has been also reported associated with the Nherf1 promoter in an “in vitro” model of colorectal cancer by β-catenin knockdown, increasing Nherf1 mRNA levels." (PMID 31336689, 2019). "The suppressor function of Wnt-β-catenin on NHERF1 by TCF4 interaction and promoter activity by T-cell factor 1 (TCF1)-Nherf1 promoter gene interaction has been reported in an in vitro model of colorectal cancer." (PMID 31336689, 2019). "NHERF1 transcripts were quantified in colorectal tissues including 64 colorectal cancer tissues and 50 adjacent normal tissues." (PMID 27999191, 2017). "A high level expression of NHERF1 was found in the colorectal cancer tissues and it was shown that NHERF1 expression was positively correlated with VEGFR2 expression." (PMID 27999191, 2017). "In the present study, a high level expression of NHERF1 was found in colorectal cancer tissues and probably contributed to the malignant phenotypes of tumor recurrence and distant metastasis." (PMID 27999191, 2017). "Overall, in the present study, a high level expression of NHERF1 was found in colorectal cancer tissues and it was shown that expression of NHERF1 was positively correlated with VEGFR2 expression." (PMID 27999191, 2017). "Here we showed that a high level expression of NHERF1 was found in colorectal cancer tissues and that the expression of NHERF1 was positively correlated with VEGFR2 expression." (PMID 27999191, 2017). "Clinical studies show an association between NHERF1 overexpression and malignant progression of colorectal cancers; however, there is very little information on the function of NHERF1 in in vitro studies specifically in colorectal cancer cells." (PMID 27999191, 2017). "The colorectal cancer tissues were separated to two subgroups, NHERF1 low level group and NHERF1 high level group, by the median value (2.0 copies) of NHERF1 transcripts quantified in colorectal tissues." (PMID 27999191, 2017). "Alterations in the apical membrane localization of NHERF1 contribute to colorectal cancer through the disruption of epithelial morphology." (PMID 27097111, 2016). "We have previously shown that the NHERF1 apical PM expression from colonic epithelial cells is lost early in the progression of colorectal cancer." (PMID 25775275, 2015).
colorectal cancer (continued). "The prognostic value of VEGFR2 expression in colorectal cancer relied on the expression of NHERF1." (PMID 27999191, 2017). "The overall survival rate analysis suggested NHERF1 could play an important role in the progression of colorectal cancer regulated by VEGFR2 signaling pathway." (PMID 27999191, 2017). "Other studies have showed that NHERF1 is considered a new player in colorectal cancer progression." (PMID 27999191, 2017). "Nuclear NHERF1 expression, which is present in the early stages of carcinogenesis in colorectal cancer and is correlated with poor prognosis, may contribute to the onset of the malignant phenotype." (PMID 27097111, 2016). "The present results suggest a dynamic interplay between NHERF1 and VEGFR2 signaling in colon cancer cells, which could explain the up-regulation of NHERF1 in colorectal cancer and the contribution of NHERF1 to the regulation of tumor cell responses to the hypoxia microenvironment." (PMID 27999191, 2017).
nephrolithiasis (9 papers, 2012 to 2024). The presence of a calculus in the pelvis of the kidney; this is most often composed of mineral salts and proteins. "Patients with mutations in NHERF-1 (SLC9A3R1) display phosphaturia and nephrolithiasis but have otherwise normal PT function." (PMID 29043081, 2017). "Hypophosphatemic Rickets with Nephrolithiasis and Osteoporosis Type 2 (NPHLOP2), caused by an inactive mutation of SLC9A3R1 (also known as NHERF1), which encodes an adaptor protein that regulates several G protein-coupled receptors including PTH1R." (PMID 33015068, 2020). "Although the site of these depositions in NHERF-1 null mice were similar to those found in human idiopathic calcium oxalate stone formers, no direct evidence of NHERF-1 mutation has shown to cause kidney stones in humans." (PMID 26185749, 2015).
breast tumors (8 papers, 2006 to 2021). "We reported three cases of NHERF1 intragenic mutations in a panel of breast tumors pre-screened for LOH; notably, all mutations were located at conserved residues of PDZ domains or ERM-interacting domain." (PMID 18190691, 2008). "LOH at the NHERF1 locus is strongly associated with aggressive features of breast tumours, implicating NHERF1 as a haploinsufficiency tumour suppressor gene." (PMID 17078868, 2006). "We reported loss of heterozygosity (LOH) at the NHERF1 gene locus (17q25.1) in more than 50% of human breast tumours." (PMID 17078868, 2006). "Loss of heterozygosity (LOH) at the NHERF1 locus is found in more than 50% of breast tumours." (PMID 17078868, 2006). "Because a majority of breast tumors lose NHERF1 expression, our present study raises a possibility of enhancing chemosensitivity by restoring NHERF1 expression." (PMID 18190691, 2008). "LOH at the NHERF1 locus is positively correlated with aggressive features of breast tumours, including tumour size, grade, and stage." (PMID 17078868, 2006). "In a panel of breast tumours pre-screened for LOH, three intragenic mutations of NHERF1 were found (approximately 3%)." (PMID 17078868, 2006). "NHERF1 expression has been reported to be up-regulated by estrogen also in breast tumors." (PMID 29029467, 2017). "NHERF1 LOH positively correlates with aggressive features of breast tumors, including tumor size, grade and stage, indicating that NHERF1 plays a critical role in mammary carcinogenesis, in which its putative suppressor activity may be haplo-insufficient." (PMID 18190691, 2008). "We showed in this study that cytoplasmic NHERF1 colocalizes with the oncogenic receptor VEGFR1 and their significant correlation suggests new potential implications in breast tumor progression." (PMID 22439624, 2012). "Nuclear NHERF1 was upregulated in tumor cells, as shown by a higher nuclear/cytopasmic ratio of NHERF1 immunofluorescence staining in breast tumor cells than in adjacent non-tumor mammary epithelial cells (p = 0.038)." (PMID 27097111, 2016). "NHERF1 protein expression was higher in the nucleus of cancer cells, as shown by a higher nucleus/cytoplasm ratio of NHERF1 staining in breast tumor cells when compared with that in non-tumor mammary epithelial cells (p = 0.038)." (PMID 27097111, 2016).
pancreatic cancer (6 papers, 2008 to 2023). "The specific cancer types used in the present study were gastric cancer (urease), blood cancer (WDR5), HCCs, and pancreatic cancer (NHERF1)." (PMID 34452553, 2021). "However, such allelic loss is infrequent in other tumor types; LOH at the NHERF1 locus occurred in fewer than 10% of colorectal and pancreatic cancer lines, suggesting that NHERF1 is specifically targeted during breast tumorigenesis." (PMID 18190691, 2008). "NHERF1-mediated functional coupling of CXCR2 and PLC-β3 will form a macromolecular complex, which is essential for CXCR2 signal transduction and malignant progression of pancreatic cancer." (PMID 37576896, 2023).
glioblastoma (5 papers, 2011 to 2023). The most malignant astrocytic tumor (WHO grade IV). "In glioblastoma, NHERF1 loss from the PM has been shown to displace PTEN from the PM and consequently activate PI3K-Akt pathaway." (PMID 25775275, 2015). "Importantly, NHERF1 overall loss or PM displacement has been reported in aggressive tumors, including carcinomas and glioblastoma." (PMID 25775275, 2015). "A dysfunctional phosphatase network comprising PTEN and PHLPP, as well as the scaffold protein NHERF1, has been recently described in glioblastoma cells." (PMID 27477328, 2017). "Most glioblastoma cases were negative for NHERF1 microlumen labeling, however, 20% showed focal microlumen formation." (PMID 25775275, 2015).
hypophosphatemia (5 papers, 2021 to 2024). Lower than normal levels of phosphates in the circulating blood. "NaPi2a, NaPi2c, and NHERF1 regulate plasma phosphate concentration by reabsorbing phosphate in proximal kidney tubules and have been found altered in monogenic hypophosphatemia with a risk of KSD." (PMID 37432176, 2023). "Another example of allosteric regulation within NHERF1 relates to Leu110Val, Glu225Lys and Arg153Gln mutations identified in patients with hypophosphatemia." (PMID 33499384, 2021). "Hypophosphatemic NL/osteoporosis 2 (OMIM phenotype number 612287) is an AD condition due to an inactivating variant in SLC9A3R1, resulting in loss of NHERF1 activity with subsequent decrease in NPT2a expression, resulting in renal phosphorus wasting with hypophosphatemia." (PMID 38606357, 2024). "Therefore, NHERF1 deficiency may indirectly provoke hyperphosphaturic hypophosphatemia with consecutive hypercalciuria, promoting the formation of calcium kidney stones and renal calcification (MIM #612287)." (PMID 37432176, 2023). "Mutations in NPT2A or NHERF1 cause elevated renal phosphate excretion and hypophosphatemia in patients, thus highlighting an essential role of the NPT2A-NHERF1 axis in bone and kidney physiology." (PMID 38465463, 2024). "Mice lacking NHERF1 and humans harboring mutations or polymorphisms in SLC9A3R1, who are haploinsufficient for NHERF1, exhibit hypophosphatemia, osteopenia, and increased fracture rates." (PMID 38465463, 2024). "Loss-of-function mutations in NHERF1 (PDZ1/L110V, PDZ2/R153Q and E225K) or NPT2A (R495H/C and S585P) disrupt phosphate metabolism and lead to hypophosphatemia." (PMID 33499384, 2021).
prostate carcinoma (5 papers, 2011 to 2025). A carcinoma that arises from epithelial cells of the prostate gland. "We found that NHERF-1 was downregulated by MINDIN in prostate cancer, causing an increase in tumor cell migration and proliferation." (PMID 33498862, 2021). "Evaluation of human and mouse prostate cancer samples showed increased MINDIN expression associated with decreased expression of the adaptor protein Na+/H+ exchanger regulatory factor 1 (NHERF-1)." (PMID 33498862, 2021). "In particular, metastastic samples have shown significantly lower staining than all other samples and tissue types, indicating that loss of NHERF-1 expression may play a critical role in prostate cancer metastasis." (PMID 33498862, 2021). "Intriguingly, both MINDIN and NHERF-1 overexpression seem to increase RANKL expression in prostate cancer cells." (PMID 33498862, 2021). "Supporting these observations, a previous study revealed that the average immunostaining intensities of NHERF-1 are lowest in the specimens of prostate cancer and in those with bone metastases compared to control samples." (PMID 33498862, 2021). "Altogether, these observations suggest that NHERF-1 mediates key cellular events induced by MINDIN during prostate cancer progression." (PMID 33498862, 2021). "We propose that MINDIN downregulates NHERF-1 expression leading to promotion of processes involved in prostate cancer progression." (PMID 33498862, 2021). "MINDIN promotes prostate cancer cell migration and proliferation via downregulation of NHERF1 levels." (PMID 33498862, 2021). "An immunohistochemical study in prostatic cancer has revealed decreased NHERF-1 presence in primary and metastatic prostatic adenocarcinoma samples." (PMID 33498862, 2021). "Upregulation of MINDIN and downregulation of NHERF-1 expression were observed both in human prostate cancer samples and in the TRAMP-C1 model." (PMID 33498862, 2021). "Our data indicate that NHERF-1 downregulation mediates MINDIN-induced prostate cancer cell migration and proliferation and modulates RANKL expression." (PMID 33498862, 2021). "Here, we describe the key role of the osteogenic factor NHERF1 as a mediator of the protumorigenic actions of MINDIN during prostate cancer progression." (PMID 33498862, 2021). "In the Oncomine database (GSE6099), NHERF1 mRNA expression is reduced in prostate carcinoma compared to PCa precursor." (PMID 33363146, 2020). "In contrast, NHERF1 immunolabeling was decreased in prostate cancer compared to control samples." (PMID 33498862, 2021). "We propose that NHERF-1 downregulation by MINDIN has a key role during prostate cancer progression." (PMID 33498862, 2021). "In the present manuscript, we used this mouse model to test whether MINDIN could regulate NHERF-1 expression in prostate cancer." (PMID 33498862, 2021). "Whether NHERF-1 translocates to the nucleus with β-catenin in any stage during prostate cancer progression would require further study." (PMID 33498862, 2021). "Nevertheless, the mechanisms that trigger NHERF-1 decreased levels in prostate cancer and the cellular processes affected in prostate cancer cells by NHERF-1 downregulation are unknown." (PMID 33498862, 2021). "We hypothesize that NHERF-1 modulation is a mechanism used by MINDIN to promote prostate cancer progression." (PMID 33498862, 2021). "Given that MINDIN induces osteomimicry in prostate cancer cells and regulates bone processes during premetastatic development, we hypothesize that regulation of NHERF-1 is one of the mechanisms used by MINDIN during prostate progression towards a bone metastatic phenotype." (PMID 33498862, 2021). "Thus, our data suggest that MINDIN could enhance the activation of the Wnt/β-catenin pathway in prostate cancer cells by promoting a decrease in NHERF-1 expression at the plasma membrane, therefore releasing the membranous fraction of β-catenin." (PMID 33498862, 2021).